FOS (Fos proto-oncogene, AP-1 transcription factor subunit)
Diseases named in the same sentence as FOS in open-access papers (continued):
Sharing a sentence is not in itself a finding about the gene and the disease.
breast carcinoma (continued). "Notably, the co-expressed gene FOS is a target for the approved anti-neoplastic drug paclitaxel, widely used in breast cancer treatment." (PMID 41123022, 2026). "Since c-FOS contributes a lot to breast cancer progression and its clinical relevance, we aimed to assess whether targeting c-FOS might be efficient for treating breast cancer progression." (PMID 40148973, 2025). "Furthermore, in mouse mammary tumor cells, c-FOS has been shown to affect cell–cell and cell–matrix adhesion." (PMID 41233892, 2025). "Interestingly, we observed that high FOS expression predicted a poor outcome for patients with HER2+ subtype breast cancer, which requires further investigation and interpretation." (PMID 37353480, 2023). "Together, our results indicate that in mammary tumor cells GATA3 directly activates the transcription of FOS to maintain their luminal and epithelial features while concurrently repressing the transcription of FOSL1 to suppress aberrant mesenchymal differentiation, i.e., inhibiting EMT." (PMID 37353480, 2023). "In addition, FOS activates Socs3 in different cell types, including pro-B lymphocytes, breast cancer cells, and NSC." (PMID 34359927, 2021). "Candidate pathways were constructed starting from the estrogen receptor ESR1 gene and targeting breast cancer-associated transcription factors, such as JUN, FOS, STAT1, STAT3, STAT5A, ELK1, and ETS1 (Target transcription factors were pre-identified by GibbsOS19)." (PMID 33432018, 2021). "In addition to those genes that encode downstream products of IL-17A/IL-17F signaling transduction, the expression levels of IFNG, FOS, FOSB1, and FOSL1 were also found to be associated with ER status in breast cancer." (PMID 33102239, 2020). "It is reported that c-FOS gene expression is activated by the combined effect of extracellular nucleotides and growth factors, which leads to increased calcium levels and proliferation in breast cancer cells." (PMID 32280695, 2020). "Simultaneously, the key genes, including ZFP36, EGR1, and FOS may be potentially effective targets of BD and also are crucial for breast cancer development." (PMID 32714860, 2020). "The present study suggested that FN1, IL6 and FOS may be potential targets in the development of treatments for breast cancer." (PMID 25824986, 2015). "Furthermore, we detected upregulation of genes that are downregulated in the primaries of breast cancer patients, including c-FOS, EGR1 and ID2." (PMID 24980816, 2014). "In addition, transcription factors known as tumor suppressors or genes related to breast cancer including c-FOS, EGR1, ID2 and SERPINB2, as well as suppression of metastasis associated genes (CD44 and IL11) have emerged as molecular targets of BSP knockdown." (PMID 24980816, 2014). "The transcription factor FOS, upregulated in all the three comparisons, is a well known protooncogene that positively regulates cell cycle progression and is induced in human breast cancer cell cultures." (PMID 22646717, 2012). "Based on published associations to breast cancer-specific tumor biology, a steroid response module (SR), a basal breast cancer module (basal), and a module containing genes (for example, FOS and EGR1) related to early response to growth factor or serum stimulation (early response) were identified." (PMID 22839103, 2012). "Therefore, we speculate that the intersecting gene c-FOS is an important target gene for the formation of NETs in breast cancer." (PMID 40148973, 2025). "As the core gene regulated by ERα, FOS might play a crucial role in ERα positive breast cancer." (PMID 30301189, 2018). "In addition, the FN1, IL6 and FOS genes were found to be involved in breast cancer development." (PMID 25824986, 2015). "Therefore, the key role of FN1, IL6 and FOS in breast cancer development has been demonstrated." (PMID 25824986, 2015). "The FN1, IL6 and FOS genes may therefore be potential targets in the treatment of breast cancer." (PMID 25824986, 2015).
breast carcinoma (continued). "Except for known disease proteins of breast cancer that found in the 6 protein complexes, many disease proteins that were associated with many other types of diseases could be found, with examples including E2F4, E2F5, HRAS, JUN, FOS." (PMID 24565064, 2014). "This methodology has been effective in uncovering optimal drug targets in various contexts, including previously established targets for breast cancer (e.g., SRC, MTOR) and spinal cord injury (e.g., TNF, FOS, IL6)." (PMID 40895536, 2025). "Briefly, SRC-1 promotes the transcriptional activityof several transcription factors, including HOXC11, PEA3, AP-1, HIF1α, c-FOS, Ets1/2, and STAT1/3, in breast cancer." (PMID 38553750, 2024). "It was reported that in breast cancer AP-1 transcription factor components, i.e., JUN, JUNB, FOS, FOSB, in addition to DUSP1, EGR1, NR4A1, IER2 and BTG2, behave as a conserved co-regulated network 14, most of which are transcriptional factors." (PMID 37057290, 2023). "The FOS, FOSB, EGR1, and EGR3 expression levels in healthy breast tissues were higher than in breast cancer tissues." (PMID 37233869, 2023). "In human breast cancers, GATA3 expression is negatively correlated with FRA1 and positively correlated with c-FOS." (PMID 37353480, 2023). "In this study, we found that in both human and mouse breast cancers GATA3 and c-FOS are preferentially expressed in luminal-type mammary tumor cells, and are very low or absent in BLBCs." (PMID 37353480, 2023). "At the mRNA level, analyses of microarray data sets representing large cohorts of breast cancer patients showed that FRA-1 mRNA level inversely correlated with DMFS (Distant Metastasis-Free Survival), while c-FOS expression exhibited the opposite correlation." (PMID 37176013, 2023). "Consistent with the findings derived from mouse models, we found that in human breast cancers, GATA3 expression is negatively correlated with FRA1 and positively correlated with c-FOS." (PMID 37353480, 2023). "Because JUN is a common component of JUN/JUN homodimers and JUN/FOS heterodimers 36, we focused to examine JUN expression in breast cancer stroma." (PMID 36438487, 2022). "As evidenced by the IC50 values, FOS stands out for its marked cytotoxicity in all the cell lines, with a greater potency in MDA-MB-468 breast cancer cells (IC50 approximately 1.4 and 2.0 times lower than those in Caco2 and H358)." (PMID 34771097, 2021). "In this review, we examine the role of crosstalk between PRLR and ERBB1/2 signaling pathways in the activation of unliganded ERα, cyclin-D1 and other oncogenic factors (MYC, FOS, JUN) in breast cancer." (PMID 34572912, 2021). "Individually, FOS and NR4A2 have been identified as potential drug targets and biomarkers for breast cancer." (PMID 34161324, 2021). "Under our experimental conditions, both FOJ and FOS extracts significantly reduced the cell viability of tested cell lines, although with more selectivity towards MDA-MB-468 breast cancer cells and a higher potency of FOS." (PMID 34771097, 2021). "Another eight ARGs (BCL2, BIRC5, EIF4EBP1, ERO1L, FOS, GAPDH, ITPR1, and VEGFA) were explored, and the author found that these genes not only were significantly associated with overall survival but also could predict distant metastasis-free survival in breast cancer." (PMID 34869345, 2021). "In the previous step, we performed a single gene characterization of the hub gene related to the overall survival rate of breast cancer, and we found that all PTGS2, ESR1, and FOS were enriched in the PPAR signaling pathway." (PMID 33149754, 2020). "FOS interacts with JUN protein family members to mediate transcriptional activation and plays a key role in breast cancer." (PMID 33149754, 2020). "Various JUN and FOS members have been found to interact with SMADs, and JUNB triggers activation of a TGFβ-induced SMAD-dependent breast cancer invasion program." (PMID 32350443, 2020).
breast carcinoma (continued). "In the present study, we demonstrated that BD significantly decreased the level of FOS mRNA and protein expression in MCF-7 and MDA-MB-231 breast cancer cells." (PMID 32714860, 2020). "Recently, on the basis of the GEO database, Gu and his colleagues constructed an ARG model consisting of eight genes (BCL2, BIRC5, EIF4EBP1, ERO1L, FOS, GAPDH, ITPR1, and VEGFA), which can be used as an independent prognostic indicator of breast cancer." (PMID 32649310, 2020). "As the malignancy of breast cancer increased, the expression of several ARGs, such as EIF4EBP1, FOS and TP63, decreased or increased." (PMID 33194339, 2020). "The levels of several TGFβ pathway genes, including TGFβ2, SMAD3, BMP4, JUN, FOS, PTGS2, CTGF, and VEGFA, were found to be higher in miR-191-overexpressing breast cancer cells." (PMID 31590453, 2019). "As JUN and FOS are both proto-oncogenes involved in cell proliferation, we investigated the effect of CAAT on breast cancer cell proliferation." (PMID 28525384, 2017). "Five genes—CYP19A1, EGFR, ESR2, FOS, and IGF1—were common among all three EDCs–PCBs, phthalates and BPA, 17β-estradiol, breast cancer, and endometriosis." (PMID 26512648, 2015). "Many of these genes have known roles in cancer gene networks such as the proto-oncogenes JUN and FOS, RAP1A (RAS-related protein 1A), ITGB5, as well as BRCA2 (Breast cancer 2, early onset) and PCNA (Proliferating cell nuclear antigen)." (PMID 26448646, 2015). "Five genes—CYP19A1, EGFR, ESR2, FOS, and IGF1—were common among all three EDCs–PCB 153, phthalates and BPA, breast cancer, and endometriosis." (PMID 26512648, 2015). "All three EDCs–PCB 153, phthalates, and BPA influenced five common genes—CYP19A1, EGFR, ESR2, FOS, and IGF1—in breast cancer as well as in endometriosis." (PMID 26512648, 2015). "Several studies investigated the expression of FOS and JUN family members at the mRNA and protein levels in breast cancer and suggested a role for these proteins as potential biomarkers in breast cancer." (PMID 24073962, 2013). "Specific pharmacological inhibitors and gene-silencing procedures were used to show that BPA induces the expression of the GPER target genes c-FOS, EGR-1, and CTGF through the GPER/EGFR/ERK transduction pathway in SKBR3 breast cancer cells and CAFs." (PMID 22552965, 2012). "For instance, Myc, CCND1, FOS and EGR3 are well-studied ERα targets promoting breast cancer growth and progression." (PMID 22125492, 2011). "Compared with c-FOS, FOXQ1 is an understudied protooncogenic transcription factor for its upstream regulators, downstream direct target genes, and mechanism-based roles in breast cancer 29-31." (PMID 36778115, 2023). "Importantly, MSCs can induce the spread of cancerous cells; Breast cancer cells treated with MSCs showed overexpression of oncogenes (NCOA4, FOS), proto-oncogenes (FYN, JUN), and EMT-specific markers, leading to breast cancer metastasis." (PMID 37849741, 2023). "When breast cancer cells were directly co-cultured with MSCs, they demonstrated substantial overexpression of oncogenes (NCOA4, FOS), proto-oncogenes (FYN, JUN), and EMT specific markers, as well as shape and growth pattern changes, resulting in breast cancer metastasis." (PMID 34736460, 2021). "Furthermore, overexpression of c-FOS gene is mediated by the G protein-coupled receptor GPR30 through E2 (17β-estradiol) and phytoestrogens in breast cancer cells." (PMID 32280695, 2020). "The results showed that potential active ingredients of Poria cocos might interfere with breast cancer through synergistic regulation of PTGS2, ESR1, and FOS." (PMID 33149754, 2020). "Potential active ingredients of Poria cocos may interfere with breast cancer through synergistic regulation of key genes (PTGS2, ESR1, and FOS) that participate in the PPAR signaling pathway." (PMID 33149754, 2020).
breast carcinoma (continued). "At three concentration of BD, 0.1, 0.5, and 1.5 μM, the expression of ZFP36 and EGR1 mRNA were increased in MCF-7 and MDA-MB-231 cells in a dose-dependent manner, while the level of FOS mRNA was significantly reduced in a concentration-dependent manner in MCF-7 and MDA-MB-231 breast cancer cells." (PMID 32714860, 2020). "Finally, the gene (FOS) from the breast cancer stage II pattern, physically interacts with JUN, a target gene of Vinblastine Breast cancer drug and with NR3C1, a target gene of Megestrol Breast cancer drug." (PMID 26892392, 2016). "In addition to FOS, FOSB has also been shown to have a function in progression of various tumour types being down-regulated in poorly differentiated mammary carcinomas." (PMID 24865347, 2014). "First, while targeting c-FOS therapy can reduce neutrophil infiltration and NETs formation in breast cancer, we did not investigate changes and interactions of other immune cells, such as T cells, within the immune environment, which requires further research in the future." (PMID 40148973, 2025). "However, GPER1 can activate additional mediators of cell survival, such as extracellular signal-related kinase 1 and 2 (ERK1/2), ELK1, CREB, and FOS that may be involved in IGFBP-3 induction upon Ful treatment in breast cancer cells." (PMID 39619437, 2024). "Thus, understanding the molecular mechanisms by which hsa-miR-5586-5p may regulate FOS expression represents a critical area for further research, with potential implications for developing targeted therapeutic strategies in HER2+ breast cancer." (PMID 39682150, 2024). "Therefore, we hypothesized that FOS, FOSB, EGR1, and EGR3 mainly function as tumor suppressor genes to inhibit the occurrence and progression of breast cancers." (PMID 37233869, 2023). "In conclusion, these findings revealed potential molecular mechanisms of BD to treat breast cancer by affecting AMIT_SERUM_RESPONSE_40_MCF10A, BILD_HRAS_ONCOGENIC_SIGNATURE, and NAGASHIMA_NRG1_SIGNALING_UP pathways and regulating expression of ZFP36, EGR1, and FOS." (PMID 32714860, 2020). "The results showed BD in breast cancer treatment may take actions through affecting AMIT_SERUM_RESPONSE_40_MCF10A, BILD_HRAS_ONCOGENIC_SIGNATURE, and NAGASHIMA_NRG1_SIGNALING_UP pathways and regulation expression of ZFP36, EGR1, and FOS(c-FOS)." (PMID 32714860, 2020). "Additionally, osteoclast differentiation and rheumatoid arthritis signaling pathways and related DEGs including FOS and CTSK may be involved in the development of bone metastasis from breast cancer." (PMID 30918839, 2019). "Finally we examined EINCR1 expression in two breast cancer cell lines and showed that, similar to FOS, it is inducible by EGF stimulation in MCF7 cells but not in MDA-MB-231 cells." (PMID 28732076, 2017). "We confirmed EGR1, FOS and EPOR as transcription targets of the EPO-EPOR signaling loop, but could not correlate the expression of different EPOR isoforms with the invasiveness of breast cancer cell lines." (PMID 24294184, 2013). "Expression levels of OXTR, FOS, ITPR1, RCAN1, CAMK2D, CACNA2D and lnc_ZFP161 were significantly down-regulated in the breast cancer tissues compared with nearby non-cancerous tissues." (PMID 33742056, 2021). "Expression levels of OXTR, FOS, ITPR1, RCAN1, CAMK2D, CACNA2D and lnc_ZFP161 were significantly down-regulated in breast cancer tissues compared with nearby non-cancerous tissues." (PMID 33742056, 2021). "We identified down-regulation of OXTR, FOS, ITPR1, RCAN1, CAMK2D, CACNA2D and lnc_ZFP161, and up-regulation of lnc_MTX2 in the breast cancer tissues compared with nearby non-cancerous tissues." (PMID 33742056, 2021). "The over-expressed CCNE1, CLGN, NEK2, PTTG1 and RAD51, and the under-expressed ADAMTS1, FOS, FOSB, IL6 and ZFP36 in tumor cells are examples of breast cancer genes without differential promoter methylation between normal and tumor samples." (PMID 25706888, 2015).
breast carcinoma (continued). "Next, an in silico analysis showed that genes related to breast cancer, including HES1, MYC, CCND1, FOS and PGR, could be regulated by NRIP1 (data not shown)." (PMID 34707101, 2021).
osteosarcoma (57 papers, 2008 to 2026). A usually aggressive malignant bone-forming mesenchymal neoplasm, predominantly affecting adolescents and young adults. "The Finkel‐Biskis‐Jinkins Osteosarcoma (c‐Fos; encoded by FOS) plays an important role in several cardiovascular diseases, including atherosclerosis and stroke." (PMID 38818568, 2024). "Retroviral FOS oncogene can cause osteosarcoma in mouse model systems, when fused with a highly active promoter and the v-fos 3’ untranslated region." (PMID 31768625, 2020). "FOS has been linked to bone tumour pathogenesis, and viral homologue v-fos causes osteosarcoma in mice." (PMID 29858576, 2018). "The transcription factor FOS has long been implicated in the pathogenesis of bone tumours, following the discovery that the viral homologue, v-fos, caused osteosarcoma in laboratory mice." (PMID 29858576, 2018). "The c-FOS gene was first described as the cellular homolog of the viral oncogene causing murine osteosarcoma, while gene knock-out mice suffered from severe defects in bone development and haematopoiesis." (PMID 26061167, 2015). "Other mutated genes implicated in osteosarcoma pathogenesis are c-FOS and TWIST." (PMID 39595017, 2024). "Studies have shown that overexpression of FOS can promote tumorigenesis and chemotherapy resistance in tumors such as ovarian cancer and osteosarcoma, and that c‐FOS expression is clinically significantly correlated with osteosarcoma recurrence." (PMID 40151836, 2025). "The discovery of the FOS retroviral homologue (v‐fos) as an initiator of osteosarcoma in mice spurred significant interest in the role of FOS and its paralogues in the pathogenesis of bone and other tumours." (PMID 36426824, 2023). "Among them, the key hub genes were ICAM1 (intercellular adhesion molecule 1), HRAS (Ras family small GTP binding protein H‐Ras), PTGS2 (prostaglandin‐endoperoxide synthase 2, also known as COX‐2), and FOS (FBJ osteosarcoma oncogene)." (PMID 36772869, 2023). "A study in osteosarcoma showed that expression of FOS protects cells from replication stress by inducing CHK1 and facilitates transformation by RAS-MAPK68." (PMID 35879366, 2022). "The expressions of the receptors for these growth factors can be regulated by AP-1 factors in Leydig cells, as shown with the upregulation of FGFR1 by FOS in osteosarcoma cells." (PMID 36361676, 2022). "FOS has been shown to be involved in cell proliferation, migration, and invasion accompanied by altered expression of Wnt family members in osteosarcoma." (PMID 33373316, 2020). "The osteosarcoma case showed, in addition to multiple copies of the FOS-locus, also multiple copies of the FOSB-locus." (PMID 31768625, 2020). "In terms of specificity, strong nuclear expression of FOS has been detected in a subset of other bone forming tumours and was only rarely present in osteosarcoma." (PMID 31741049, 2020). "Two of 21 osteoblastomas were FOSB positive (in addition to FOS), while all 22 osteoid osteomas, all 3 osteoblastoma-like osteosarcomas, and both cases with reactive callus formation were negative." (PMID 31768625, 2020). "Transgenic mice overexpressing the c‐Fos proto‐oncogene in bone develop osteosarcomas and coexpression of a c‐jun transgene can enhance FOS‐induced oncogenesis." (PMID 29744300, 2018). "We examined FOS immunoreactivity in 183 cases of osteosarcoma, including 97 cases of osteoblastic osteosarcoma, and 17 cases of angiosarcoma." (PMID 29858576, 2018). "Direct co-regulation has been observed between TUBB, RPLPO and ACTB via v-myc myelocytomatosis viral (MYCN) and between TUBB and RPLPO via FBJ murine osteosarcoma viral (FOS)." (PMID 25881111, 2015). "In osteosarcoma c-FOS is amplified leading to its over expression however in the other tumour types, the role of amplification in the gene overexpression is unresolved." (PMID 19506729, 2008).